HOTAIR (HOX transcript antisense RNA)
Diseases named in the same sentence as HOTAIR in open-access papers (continued):
Sharing a sentence is not in itself a finding about the gene and the disease.
CNS disorders (1 paper, 2022). "Here, we reviewed the research results of HOTAIR in CNS disorders to provide new insights into the pathogenesis, diagnostic value, and therapeutic target potential of HOTAIR in human CNS disorders." (PMID 35813070, 2022). "Currently, there are only few studies on HOTAIR as a diagnostic marker of CNS disorders, and these studies remain at the level of HOTAIR expression." (PMID 35813070, 2022). "Moreover, emerging evidence confirms that HOTAIR is also widely involved in the pathogenesis of CNS disorders and can be a potential diagnostic marker and therapeutic target of CNS disorders." (PMID 35813070, 2022). "Finally, the potential of HOTAIR as a disease diagnostic biomarker of CNS disorders is highlighted." (PMID 35813070, 2022). "Dysregulated HOTAIR expression has been found in various pathological processes, including in CNS disorders." (PMID 35813070, 2022). "In conclusion, recent studies have shown that HOTAIR is involved in the occurrence and development of several CNS disorders and may be a potential biomarker for disease diagnosis and prognosis." (PMID 35813070, 2022). "Recent studies have shown that HOTAIR may participate in the regulation of the occurrence and development of CNS disorders." (PMID 35813070, 2022). "However, there are few studies on HOTAIR regulation of protein ubiquitination, and the role of HOTAIR in the ubiquitination process of different proteins in CNS disorders still needs to be further studied." (PMID 35813070, 2022). "In vitro and in vivo studies have shown that inhibition of HOTAIR expression can play a therapeutic role in CNS disorders through multiple mechanisms, suggesting it may be a potential therapeutic target for CNS disorders." (PMID 35813070, 2022). "HOTAIR may exert diverse functions in modulating pathological processes in different types of CNS disorders." (PMID 35813070, 2022). "HOTAIR plays an important role in the development of CNS disorders." (PMID 35813070, 2022). "In addition, HOTAIR has the potential to become a new biomarker for the diagnosis and prognosis assessment of CNS disorders and even provide a new therapeutic target for CNS disorders." (PMID 35813070, 2022). "Therefore, HOTAIR expression may be involved in the development of CNS disorders by inhibition of inflammatory responses and release of inflammatory factors." (PMID 35813070, 2022). "However, whether HOTAIR plays a role in CNS disorders by regulating cell cycle remains to be further determined." (PMID 35813070, 2022).
infectious disease (1 paper, 2022). A disorder directly resulting from the presence and activity of a microbial, viral, or parasitic agent in humans. "Interestingly, in HCV-4 patients, HOTAIR could serve as a risk assessment biomarker following direct-acting antiviral therapy, suggesting that HOTAIR has potential as a biomarker for the treatment or risk evaluation of infectious diseases." (PMID 35335994, 2022).
inflammation (1 paper, 2021). Aberrant reaction of the microcirculation characterized by movement of fluid and leukocytes from the blood into extravascular tissues. "This study was the first to explore the mechanism of the interaction between miR-138 and HOTAIR in the myocardial inflammation induced by H/R." (PMID 34970356, 2021).
HOTAIR also shares sentences with these, for which no sentence is quoted: adenocarcinoma (7 papers); breast (6); brain tumors (5); cancers of the digestive system (5); Fibroadenoma (4); head and neck cancer (4); stomach adenocarcinoma (3); benign prostate hyperplasia (2); cervical squamous cell carcinoma (2); clear cell renal cell carcinoma (2); colorectal adenocarcinoma (2); digestive system carcinoma (2); endocervical adenocarcinoma (2); hematological malignancies (2); hepatitis B (2); metastatic prostate carcinoma (2); polycystic ovary syndrome (2); systemic lupus erythematosus (2); uveal melanoma (2); acute kidney injury (1); acute myocardial infarction (1); aortic stenosis (1); asthma (1); autoimmune disease (1); B cell lymphoma (1); bipolar disorder (1); bladder (1); blood cancers (1); brain glioma (1); cancers of the respiratory system (1).
A further 42 diseases each share a sentence with HOTAIR in 1 paper.